TRPM1 (transient receptor potential cation channel subfamily M member 1)
Description:
Constitutively open nonselective divalent cation-conducting channels which mediate the influx of Ca(2+), Mg(2+), Mn(2+), Ba(2+), and Ni(2+) into the cytoplasm, leading to membrane depolarization. Impermeable to zinc ions. In addition, forms heteromultimeric ion channels with TRPM3 which are permeable for calcium and zinc ions. Plays an essential role for the depolarizing photoresponse of retinal ON bipolar cells. In the dark, tonic release of glutamate activates the G protein-coupled receptor for glutamate, GRM6, its activation induces the release of G(o) protein and the beta-gamma G protein dimer. Both subunits can interact and inactivate the TRPM1 channel. A light onset, induces decrease in glutamate release and deactivation of GRM6 leading to channel opening and membrane depolarization (By similarity). May play a role in metastasis suppression.
Synonyms: LTrpC1; MLSN1; CSNB1C
Tractability: Small molecule: it belongs to a druggable protein family. Antibody: UniProt places it where antibodies can reach, with high confidence; its Gene Ontology location is reachable by antibodies, with high confidence; UniProt predicts a signal peptide or a membrane-spanning region. PROTAC: ubiquitination databases record sites on it.
Chemical probes: ML329
Gene: Protein-coding gene on chromosome 15 (31,001,065 to 31,161,160, reverse strand). Ensembl gene ENSG00000134160.
Subcellular location: Cell membrane; Endoplasmic reticulum membrane; Cell projection, axon
Subcellular location (Human Protein Atlas): Centriolar satellite; Golgi apparatus; Plasma membrane
Pathways (Reactome):
Developmental Biology: Regulation of MITF-M-dependent genes involved in apoptosis
Transport of small molecules: TRP channels
Gene Ontology:
Molecular function: calcium channel activity; monoatomic cation transmembrane transporter activity; protein binding; monoatomic ion channel activity
Biological process: calcium ion import across plasma membrane; cellular response to light stimulus; G protein-coupled glutamate receptor signaling pathway; monoatomic cation transmembrane transport; visual perception; calcium ion transmembrane transport; calcium ion transport; monoatomic ion transport; protein tetramerization; transmembrane transport
Cellular component: endoplasmic reticulum; endoplasmic reticulum membrane; plasma membrane; axon; membrane
Genetic constraint (gnomAD): Loss-of-function variants: 112 observed, 156.09 expected, observed/expected ratio (o/e) 0.72, 90% interval 0.62 to 0.84. The upper end of that interval is the gene's LOEUF score, 0.84, which puts it in group 3 of 6, group 1 being the genes least tolerant of losing a copy. Missense variants: 1,966 observed, 2,140.9 expected, observed/expected ratio (o/e) 0.92, 90% interval 0.88 to 0.95. Synonymous variants: 740 observed, 799.21 expected, observed/expected ratio (o/e) 0.93, 90% interval 0.87 to 0.98.
Homologues: Orthologues: chimpanzee TRPM1 (99% identical), macaque TRPM1 (98% identical), dog TRPM1 (91% identical), rabbit TRPM1 (91% identical), guinea pig TRPM1 (88% identical), rat Trpm1 (87% identical), mouse Trpm1 (87% identical), pig TRPM1 (86% identical), tropical clawed frog trpm1 (76% identical), zebrafish trpm1a (65% identical), zebrafish trpm1b (63% identical), Drosophila melanogaster Trpm (38% identical), and 4 more. Paralogues in human: TRPM3 (61% identical), TRPM7 (45% identical), TRPM6 (43% identical), TRPM2 (24% identical), TRPM4 (22% identical), TRPM5 (20% identical), TRPM8 (19% identical).
Diseases named in the same sentence as TRPM1 in open-access papers:
TRPM1 is named in the same sentence as 75 diseases in open-access papers, as found by Europe PMC text mining. Sharing a sentence is not in itself a finding about the gene and the disease. The quoted sentences say what the papers report.
melanoma (76 papers, 2010 to 2025). A malignant, usually aggressive tumor composed of atypical, neoplastic melanocytes. "Among the TRPM subfamily, TRPM1 was the first identified in melanoma and is associated with tumor progression and survival, potentially through CaMKII-mediated activation of AKT signaling, thereby enhancing colony formation and tumor growth." (PMID 41155636, 2025). "In fact, quantification of TRPM1 mRNA by chromogenic in situ hydridization (CISH) revealed a steep TRPM1 loss at the transition of the melanoma from the radial growth phase into the vertical growth phase, with adverse prognostic significance." (PMID 37240443, 2023). "TRPM1 was also identified as a potential risk gene (along with 35 other genes) in familial melanoma." (PMID 37240443, 2023). "Though beyond the scope of this review, it is worth mentioning that autoantibodies are responsible for the melanoma-associated retinopathy target TRPM1 cation channel of retinal ON bipolar cells." (PMID 37240443, 2023). "TRPM1 or melastatin was the first protein of this subfamily to be identified while searching for loci associated with melanoma." (PMID 36844925, 2022). "Reduced expression of TRPM1 is associated with lower melanin synthesis and its loss of expression is a prognosis marker of primary melanoma." (PMID 33291725, 2020). "For instance, decreased TRPM1 is linked to the aggressiveness of melanoma tumours and poor overall survival of melanoma patients, suggesting a tumour suppressor role for TRPM1." (PMID 32575381, 2020). "In line with this assumption, the induction of cellular differentiation in melanoma cells by treatment with hexamethylenbisacetamide caused an upregulation of TRPM1 transcripts." (PMID 30248976, 2018). "In contrast, in metastatic melanoma, where TRPM1/miR-211 levels do not show a further decrease compared to patients with primary melanoma, the patients associated with longer OS are those with low TRPM1 levels." (PMID 28445987, 2017). "Levels of Trpm1 mRNA expression among B16 melanoma variants were in the descending order BL6, F1, and F10, but were not affected by acidic pHe." (PMID 29108231, 2017). "TRPM1 has also long been linked to melanoma, where reduced levels of TRPM1 expression and the appearance of alternatively spliced forms of TRPM1 mRNA are correlated with a less differentiated and more malignant phenotype." (PMID 27983625, 2016). "As a matter of fact, several studies point to TRPM1 as a tumor suppressor in melanoma cells, as its loss of expression correlates with melanocytic tumor progression, metastatic potential, tumor thickness, and overall melanoma tumor aggressiveness." (PMID 25710007, 2015). "Further screening of serum from melanoma patients will be necessary to determine the prevalence of TRPM1 as a melanoma-associated antigen." (PMID 23936334, 2013). "Although downregulation or loss of TRPM1 expression has been reported in melanoma metastasis, this study cannot compare TRRM1 expression levels between original cutaneous melanoma and lung metastasis in this case due to lack of original melanoma specimens." (PMID 23148706, 2012). "The transcript sequence for this miRNA is located in the sixth intron of TRPM1 gene, locus that encodes genes that was previously suggested as melanoma aggressiveness suppressors." (PMID 21860617, 2012). "TRPM1 was originally identified as a marker associated with aggressiveness of murine melanoma and growth inhibition in human melanoma cell lines." (PMID 22545195, 2010). "Importantly, the TRPM1 gene locus also encodes microRNAs (e.g., miR-211), which are themselves implicated in melanoma progression and regulation of oncogenic pathways." (PMID 40869148, 2025). "Therapeutic strategies aimed at restoring or mimicking TRPM1 that function either directly or via the modulation of associated microRNAs—such as miR-211—are under investigation as potential interventions to curb melanoma progression." (PMID 40869148, 2025).
melanoma (continued). "It has also been linked to disease-free survival in patients with melanoma, suggesting that TRPM1 may function as a metastatic suppressor." (PMID 39108834, 2024). "Subsequent study confirms that loss of TRPM1 predicts the poor prognosis of patients with melanoma." (PMID 31519770, 2019). "In addition, our findings allow reconciling the apparent paradox that is associated with TRPM1/miR-211 behavior in melanoma: in the transition from nevi to primary melanoma TRPM1/miR-211 levels are very often down-regulated or lost." (PMID 28445987, 2017). "MiR-211 is encoded within the sixth intron of TRPM1, a candidate suppressor of melanoma metastasis, and previous researches demonstrated that overexpression of miR-211 inhibited both anchorage-independent colony formation and invasion, through regulation of IGF2R, TGFBR2, NFAT5 and BRN2." (PMID 23155457, 2012). "miR-211 is encoded within the sixth intron of TRPM1, a candidate suppressor of melanoma metastasis." (PMID 21072171, 2010). "While it is possible that TRPM1 activity, per se, contributes to melanoma progression and invasiveness, a more likely mechanism arises from the fact that miRNA 211, a tumor suppressor miRNA, is encoded in one of the introns of the TRPM1 gene and its transcription is co-regulated with that of TRPM1." (PMID 27983625, 2016). "Expression of TRPM1 gene in melanocytes is positively correlated with melanin content and negatively correlated with melanoma." (PMID 39975073, 2025). "Initially, TRPM1 was identified as a transcript enriched in human melanomas and was suggested to be a potential tumor suppressor." (PMID 41118703, 2025). "TRPM1 is implicated as a tumor suppressor, whereas TRPM7, TRPV1, and TRPV4 often function as both melanoma suppressor or oncogenic drivers, modulating proliferation, apoptosis, and metastasis." (PMID 40869148, 2025). "The TRPM1 gene influences melanoma behavior through the generation of the following two distinct transcripts: the TRPM1 channel protein, encoded by its exons, and microRNA-211, located within its sixth intron." (PMID 40869148, 2025). "For example, TRPM1 was initially discovered as a prognostic marker in melanoma, leading to its designation as “melastatin”." (PMID 41155636, 2025). "TRPM1-mediated calcium signaling appears to restrain cell proliferation and invasion, although its exact molecular functions in melanoma remain under investigation." (PMID 40869148, 2025). "TRPM1 has been implicated in tumor suppression, while TRPM7, TRPV1, and TRPV4 have been observed to function as both melanoma suppressors and oncogenic drivers, modulating proliferation, apoptosis and metastasis." (PMID 40869148, 2025). "TRPM1 (melastatin), originally identified as a melanocyte differentiation marker, is notably downregulated in advanced melanomas compared to benign nevi and normal melanocytes." (PMID 40869148, 2025). "Next, between August 6, 2021 and August 4, 2022, there was a substantial increase in detectable TRPM1 autoantibodies in the patient’s serum, which preceded a melanoma relapse (leptomeningeal disease) in September 2022." (PMID 39318594, 2024). "As the first discovered member of the TRPM channels family, TRPM1 has been found to negatively correlate with the aggressiveness of melanoma cells." (PMID 39633507, 2024). "TRPM1 has been demonstrated to increase Ca2+ levels in melanoma cells and motivate CaMKII, which in turn activates AKT, accelerating tumor progression." (PMID 39633507, 2024). "TRPM1 received the name Melastatin due to its initial discovery in the B16 mouse melanoma cell line." (PMID 39108834, 2024). "TRPM1 is involved in Melanoma progression, where expression of TRPM1 inversely correlates with tumor aggressiveness and tumor thickness." (PMID 39108834, 2024). "In primary melanoma lesions, reduced TRPM1 expression correlates with increased tumor thickness, suggesting its potential as a predictor of human melanoma development in clinical settings." (PMID 39633507, 2024).
melanoma (continued). "Melanomas with strong and uniform TRPM1 mRNA CISH positivity are aggressive, commonly with early metastasis and death." (PMID 37240443, 2023). "This unique microRNA was shown to play a key role in facilitating the tumor suppressor function of TRPM1 by inhibiting malignant melanoma progression." (PMID 37445615, 2023). "The first identified mammalian TRPM, TRPM1, was originally named melastatin because its expression levels were inversely correlated with metastatic potential in some melanoma cell lines." (PMID 37894842, 2023). "Taken together, the results demonstrated important roles for TRPM2, TRPM1, and potassium gating in the progression of melanoma." (PMID 37445615, 2023). "Together, TRPM1 and miR-211 can serve as potential targets for treatment as they are key regulators with significant function in melanoma." (PMID 37445615, 2023). "Collagen stiffness induced the expression of melanoma differentiation genes TRPM1, PMEL, TYR and MLANA, as well as well as the proliferation and survival genes CDK2 and BCL2A1." (PMID 36135194, 2022). "We also examined the expression of other genes involved in melanin synthesis, such as Mlana, Pmel and Trpm1, which are considered as biomarkers for melanoma and the results showed that these genes were significantly upregulated as well in CKO mice." (PMID 36120581, 2022). "TRPM1 is, though, described as a marker of melanoma aggressiveness and low expression is related to higher invasiveness." (PMID 33827643, 2021). "TRPM1 gene expression has been inversely correlated with the aggressiveness of melanoma malignant cells, thus suggesting its role as a tumor suppressor gene." (PMID 33076385, 2020). "TRPM-1 is an important mediator of calcium influx in cells and has been described as a tumor suppressor in melanoma." (PMID 33256110, 2020). "TRPM1/miR‐211 levels are frequently downregulated or lost during the transition from nevi to primary melanoma, and high TRPM1 levels correlate with longer disease‐free survival in primary melanoma patients." (PMID 30499222, 2019). "The TRPM subfamily consists of 8 members, TRPM1-8, named based upon the first member, i.e., TRPM1, that has been first identified as tumor suppressor in melanoma." (PMID 32038296, 2019). "In conclusion, the decreased expression of TRPM1 in melanoma development correlates with the melanoma cell transition from a low to a high metastatic phenotype, as well as with patient prognosis." (PMID 29875336, 2018). "The role of TRPM5 channels has been shown in lung cancer, TRPM1 in melanoma, and TRPM4 channel in prostate cancer as well." (PMID 29875336, 2018). "For example, the founding member, TRPM1 was first described as a gene downregulated in melanoma cells as compared to benign melanocytes." (PMID 30248976, 2018). "TRPM1 expression steadily decreases during the progression of primary cutaneous and vertical growth phase melanomas." (PMID 29875336, 2018). "Although the level of expression of TRPM1 is inversely correlated with metastasis of human melanoma." (PMID 29108231, 2017). "The transient receptor potential cation channel subfamily M member 1 (TRPM1) Ca2+ channel was identified as a putative tumor suppressor in melanomas, and its expression negatively correlated with tumor aggressiveness." (PMID 28596940, 2017). "When melanoma cells with high MITF levels were transfected with a vector for expression of OCT4 there was a reduction of both TRPM1 and TYR expression." (PMID 29044103, 2017). "Melastatin-1 is initially identified in melanoma cells so that the TRPM-1 is termed because of its homology with melastatin-1." (PMID 29238714, 2017). "Transient receptor potential cation channels (TRPM1, 2,7 and 8) have been shown to be upregulated in melanomas, where they contributed to increased proliferation and metastatic capacity." (PMID 28596940, 2017).
melanoma (continued). "It has been proposed that TRPM1 expression in melanocytes and melanoma cells is regulated by a promoter region of the gene that contains four microphthalmia transcription factor (MITF) binding sites." (PMID 25710007, 2015). "Specifically, TRPM1 was designated as a melanoma metastasis suppressor based on its expression in normal pigment cells in the skin and its absence in aggressive ocular metastatic -competent melanomas." (PMID 26818117, 2015). "TRPM1 was first discovered in B16 mouse melanoma cell lines as a result of a differential display analysis." (PMID 25710007, 2015). "Several groups demonstrated that MITF directly regulates the expression of TRPM1 in vitro and in vivo during melanoma progression." (PMID 25710007, 2015). "TRPM1 was designated as a melanoma metastasis suppressor based on its expression in normal pigment cells in the skin and the eye since it was absent in aggressive, metastasis-competent melanomas." (PMID 26605361, 2015). "Similar to TRPM1 protein, miR-211 is highly expressed in melanocytes and nevi and is reduced in melanoma cells." (PMID 25710007, 2015). "Recently miR-211, which is cotranscribed with TRPM1, has been shown to be expressed in normal melanocytes but reduced in melanoma." (PMID 24167615, 2013). "Other TRP subfamilies have also been demonstrated in the cancer development, such as TRPM1 in melanoma, TRPM7 in human retinoblastoma cells and human head and neck carcinoma cells, TRPM8 and TRPV6 in prostate cancer." (PMID 23840757, 2013). "Recently, TRPM1 is identified as a suspected target of the autoantibodies produced in melanoma patients with MAR." (PMID 23148706, 2012). "In conclusion with this findings, if MITF is reduced in melanoma cells, it will have less expression of TRPM1 and consequently of miR-211." (PMID 21860617, 2012). "TRPM1 channels on the ON bipolar dendritic tips in the OPL were specifically targeted and TRPM1 antigens were also detected in the metastatic melanoma cells in the lung." (PMID 23148706, 2012). "The immunohistochemical data provide evidence of autoantibodies against the TRPM1 cation channel on retinal ON bipolar cells and metastatic melanoma cells in paraneoplastic vitelliform retinopathy." (PMID 23148706, 2012). "The TRPM1 gene, which contains miR-211 sequences in the sixth intron, was previously suggested to be a suppressor of melanoma aggressiveness." (PMID 21072171, 2010). "Of interest, some of the miRs are found within genes of particular relevance to melanoma biology, for example: TRPM1." (PMID 20300190, 2010). "In summary, it appears that decreased levels of TRPM1 and miR-211 are observed in melanoma." (PMID 37445615, 2023). "TRPM1 gene expression has been identified in benign nevi, dysplastic nevi, and cutaneous melanomas, with a negative association between its presence and melanoma aggressiveness." (PMID 37892239, 2023). "In melanoma cells, TRPM1 is prevalent in highly dynamic intracellular vesicular structures." (PMID 38123150, 2023). "Although TRPM1 expression does not reliably distinguish between benign nevi and malignant melanoma, the loss of TRPM1 mRNA in melanoma predicts metastatic disease and poor survival." (PMID 37240443, 2023). "The TRPM1 channel in terms of potential regulatory function was recently associated with AKT activation, colony formation, cell mobility, and xenograft tumor growth in melanoma cells." (PMID 37894842, 2023). "The first characterized member of the TRPM subfamily is TRPM1, widely expressed in retina ON-bipolar cells and downregulated in aggressive metastatic melanoma cells, thus representing a potential marker for melanoma clinical diagnosis." (PMID 36613628, 2022). "TRPM1 is highly expressed in dysplastic and benign nevi, as well as in cutaneous melanomas, and variably extracted from invasive melanoma, while reduced expression was found in more advanced melanomas." (PMID 36844925, 2022).